IL6 (interleukin 6)
Diseases named in the same sentence as IL6 in open-access papers (continued):
Sharing a sentence is not in itself a finding about the gene and the disease.
chronic kidney disease (continued). "Beyond ASSAIL-MI, the RESCUE study (NCT03926117; Trial to Evaluate Reduction in Inflammation in Patients with Advanced Chronic Renal Disease Utilizing Antibody-mediated IL-6 Inhibition) targeted IL-6 ligand in patients with chronic kidney disease at high risk for cardiovascular complications." (PMID 37259918, 2023). "In particular, the rs1800629 and rs1800795 polymorphisms of TNFA and IL6 genes can selectively affect spontaneous production of inflammatory cytokines influencing kidney function decrease and consequent development and progression of chronic kidney disease." (PMID 35205271, 2022). "Interestingly, both cytokines (IL1A and IL-6) have been implicated as key factors linking malnutrition, accelerated atherogenesis, and excessive morbidity and mortality in end-stage renal disease (ESRD) patients in hemodialysis." (PMID 31924810, 2020). "Furthermore, the CDDP group also showed the highest level of IL-6 and IL-12, which have been observed to be associated with cisplatin ototoxicity as well as with acute and chronic kidney disease." (PMID 31810241, 2019). "Similarly, chronic kidney disease has been associated with elevated IL-6 levels." (PMID 39860340, 2025). "sTM was more related to the primary cause of chronic kidney disease (CKD) compared with vWF and IL-6." (PMID 36046203, 2022). "Additionally, it was demonstrated in patients with chronic kidney disease that higher levels of pro-inflammatory cytokines (i.e., IL-6) were associated with fatigue measured with the SF-36, which included mostly elements of the psychosocial and somatic fatigue dimensions." (PMID 32528052, 2020). "In addition, other authors have reported better prognosis in CC homozygous patients of IL-6 promoter polymorphism (-174 G/C) in various diseases, such us different types of cancer, surgical coronary revascularization and end-stage renal disease on hemodialysis." (PMID 27834822, 2016). "Clinically, higher baseline levels of IL-6 and C-reactive protein predict faster eGFR decline and progression to end-stage renal disease in human CKD cohorts, and elevated circulating TNF receptors 1 and 2 have been shown to forecast ESRD in diabetic patients." (PMID 40990676, 2026). "Patients with chronic kidney disease (CKD) exhibit elevated CD14++CD16+ pro-inflammatory monocytes in bone marrow alongside heightened systemic levels of IL-6, IL-1β, and TNF-α, suggesting persistent innate immune activation." (PMID 40746537, 2025). "EVs extracted from umbilical cord-derived MSCs have attenuated TNF-α, IL-6, and IL-1β levels, and increased IL-10 level in a model of chronic renal failure following I/R injury." (PMID 40535418, 2025). "IL-6 signaling has also been shown to play important roles in the pathogenesis of various kidney disorders, including chronic kidney disease (CKD), diabetic nephropathy (DN), acute kidney injury (AKI), and autosomal dominant polycystic kidney disease (ADPKD)." (PMID 40570958, 2025). "CKD: Chronic kidney disease; eGFR: estimated glomerular filtration rate; IL-6: interleukin-6; ADMA: asymmetric dimethylarginine; RBC: red blood cells; LVEF: left ventricular ejection fraction; NT-proBNP: N-terminal pro–B-type natriuretic peptide." (PMID 41450363, 2025). "Previous studies linked CX3CL1-CX3CR1 signaling to acute and chronic kidney disease and reported elevated levels of IL-6 and IL-12 in chronic kidney disease." (PMID 39844894, 2025). "IL-6 signaling via JAK/STAT has been implicated in a number of fibrotic kidney diseases, such as lupus nephritis, diabetic nephropathy, and chronic kidney disease." (PMID 41394604, 2025). "Plasma IL-6 was independently shown to predict overall and cardiovascular mortality in patients across different stages of chronic kidney disease." (PMID 40336184, 2025).
chronic kidney disease (continued). "The ZEUS trial, which is evaluating interleukin-6 inhibition with ziltivekimab in patients with cardiovascular disease, chronic kidney disease, and systemic inflammation, is highly anticipated for its potential to reshape cardiovascular risk management." (PMID 41286084, 2025). "Urinary IL-6 also seems to be able to distinguish acute from chronic kidney disease, albeit this is a conclusion based on a study carried out in dogs." (PMID 40142279, 2025). "Chronic kidney disease is characterized by a persistent state of low-grade inflammation driven by elevated cytokines such as interleukin-6 (IL-6), tumor necrosis factor-α (TNF-α), and C-reactive protein (CRP)." (PMID 41552179, 2025). "The present work analyses the renoprotective potential of clinically relevant IL-6 signaling inhibitors in acute kidney injury, chronic kidney disease, and kidney transplantation with focus on current achievements and future prospects." (PMID 39723211, 2024). "Patients with chronic kidney disease who were either infected with or vaccinated against SARS-CoV-2 had higher levels of IL-6 and IFN-γ, compared to healthy unvaccinated individuals." (PMID 38612524, 2024). "In the Chronic Renal Insufficiency Cohort (CRIC) study, biomarkers of inflammation (IL-1β, IL-1 receptor antagonists, IL-6, TNF-α, CRP, and fibrinogen) were negatively associated with renal function and positively associated with proteinuria." (PMID 39126619, 2024). "Chronic renal failure patients and animal models of acute kidney injury (AKI) caused by nephrotoxic drugs have shown increased levels of IL-6, IL-1β, and TNF-α." (PMID 39468702, 2024). "Possible markers with great potential to predict severe forms of COVID-19 disease in patients with acute or chronic kidney disease are C-reactive protein, procalcitonin, interleukin-6, prothrombin, D-dimers, and serum concentration of platelets." (PMID 39252712, 2024). "Animal data and accumulating clinical experience strongly suggest that suppression of IL-6 signaling pathways bears therapeutic potential in acute and chronic kidney diseases." (PMID 39723211, 2024). "In analyses stratified by IL‐6 levels, the association between chronic kidney disease and concentration of NfL, t‐tau, and GFAP was stronger in participants with high levels of IL‐6 than in those with low IL‐6." (PMID 38717935, 2024). "The ZEUS study is now underway to evaluate the effect of IL-6 inhibition with ziltivekimab in patients with cardiovascular disease, chronic kidney disease and inflammation (ClinicalTrials.gov Identifier: NCT05021835)." (PMID 39160276, 2024). "Several large cohort studies have confirmed the direct relationship between high circulating IL-6 levels and reduced kidney function in patients with chronic kidney disease (CKD)." (PMID 39749325, 2024). "Chronic kidney disease features heightened levels of pro-inflammatory cytokines, including IL-1, IL-6, and TNF-α." (PMID 38766523, 2024). "EPCs were also associated with older age, some comorbid conditions (chronic kidney disease, chronic lung disease, and immunocompromise), worse pulmonary ordinal scale at baseline, and increasing levels of CRP and IL-6." (PMID 39271151, 2024). "Nevertheless, cardiovascular adverse events in patients with chronic kidney disease are consistently predicted by proinflammatory cytokines, especially IL-6." (PMID 38921685, 2024). "Usually, end-stage renal disease is linked to a variety of changes in the immune system and both anti-inflammatory interleukin (IL-10) and proinflammatory cytokines (TNF-, IL-6) are elevated." (PMID 38206949, 2024). "A chronic inflammatory state induced by chronic kidney disease leads to proteolysis and appetite suppression in dialysis patients due to the release of cytokines such as interleukin-6 and tumor necrosis factor alpha." (PMID 37840653, 2023).
chronic kidney disease (continued). "Conversely, Hung and coworkers, including 338 chronic kidney disease patients in stages 3–5 in their study, demonstrated that hypervolemic patients not only had elevated IL-6 levels but also significantly increased TNF-α levels." (PMID 38139378, 2023). "The RESCUE trial included subjects with moderate-to-severe chronic kidney disease and hsCRP of >2 mg/L, administered with either placebo or ziltivekimab, a novel IL-6 monoclonal antibody, over a period of 2 years." (PMID 37600028, 2023). "In the recent RESCUE (Reduction in Inflammation in Patients with Advanced Chronic Renal Disease Utilizing Antibody-Mediated IL-6 Inhibition) trial, a significant reduction in high-sensitivity C-reactive protein (hsCRP) was observed." (PMID 37298597, 2023). "The anti-inflammatory drug ziltivekimab was effective in reducing IL-6 and subsequent hsCRP levels in patients with chronic kidney disease." (PMID 37485268, 2023). "The level of IL-6 is oftentimes elevated in the group of chronic kidney disease patients, above all, in those treated with haemodialysis." (PMID 37629400, 2023). "Chronic mediators of inflammation, such as tumor necrosis factor alpha (TNF-α), interleukin 6 (IL-6) and liraglutide, have shown increased levels in patients with chronic kidney disease." (PMID 37675359, 2023). "Deceased patients with end-stage renal disease presented higher levels of both cfDNA and inflammatory markers (IL-6 and C-reactive protein), compared with living subjects." (PMID 37685683, 2023). "The results showed that patients who started treatment at AKI1 stage had a greater decrease in IL-6 levels than those who started treatment later or had end-stage renal disease (P = 0.027)." (PMID 36249210, 2022). "Interleukin-6 (IL-6) has been identified as an important pro-inflammatory factor involved in mediating the severity of chronic kidney disease (CKD)." (PMID 35887619, 2022). "There have been many experimental studies and clinical observations showing that TNF-α and IL-6 also play a major role in the pathogenesis of chronic kidney disease through the induction of inflammatory processes." (PMID 35054932, 2022). "In our study, we reported higher levels of markers of oxidative stress and inflammation, MPO, CU/Zn SOD and IL-6, in more severe stages of chronic kidney disease (stages G4 and G5)." (PMID 36498741, 2022). "Serum IL-6, MCP-1, and NF-κB are independent risk factors for the occurrence of end-stage renal disease in patients with diabetic nephropathy." (PMID 35756496, 2022). "In a Swedish cohort of males with chronic kidney disease (n = 418), each unit increase in the PDI was associated with significantly decreased CRP and IL-6 concentrations." (PMID 36558530, 2022). "Multivariate analysis showed that serum IL-6, MCP-1, and NF-κB were independent risk factors for the development of end-stage renal disease in patients with diabetic nephropathy." (PMID 35756496, 2022). "Clinical data show serum IL-6 levels are elevated in hemodialysis patients and chronic kidney disease patients with vascular calcification." (PMID 35402550, 2022). "The Chronic Renal Insufficiency Cohort (CRIC) study has demonstrated that elevated levels of IL-6 in CKD patients resulted in a greater decline of estimated glomerular filtration rate (eGFR) but lose their significance after adjustment for albuminuria." (PMID 33670423, 2021). "Activation of the complement cascade and pro-inflammatory cytokines (CK) such as Tumor Necrosis Factor α (TNF-α) and Interleukin-6 (IL-6) can alter GFB function, causing acute glomerular injury and progression toward chronic kidney disease." (PMID 34359843, 2021). "Chronic inflammatory states are commonly found in patients with end-stage renal disease, and inflammatory cytokines, including IL-6, IL-1, TNF-a and CRP play an important role." (PMID 33413177, 2021).
chronic kidney disease (continued). "Another large cohort study, CRIC (Chronic Renal Insufficiency Cohort), found that plasma IL‐6 level is an independent and consistent predictor of AF in patients with chronic kidney disease." (PMID 33664879, 2021). "IL-1β, IL-6, and TNFα are important cytokines that serve as essential mediators of the immune response and inflammatory reactions in patients with chronic renal failure." (PMID 34463195, 2021). "Our aim was to study how specific polymorphisms of IL6 and PTX3 encoding genes affect the inflammatory response and outcome of end-stage renal disease (ESRD) patients on dialysis." (PMID 34285273, 2021). "Some studies have shown that interleukin-6 and tumor necrosis factor-α were involved in appetite suppression in patients with chronic kidney disease." (PMID 34093720, 2021). "Supplementation of HAM-RS2 led to a decrease in serum IL-6 and TNFα in end-stage renal disease patients." (PMID 34354689, 2021). "Increased serum or plasma concentrations of inflammatory markers, including CRP, interleukin 6 and TNFα are consistently reported in patients with chronic kidney disease." (PMID 34827620, 2021). "In earlier studies, Korish (2010) reported that supplementation of antioxidants to rats significantly reduced interleukin-6 levels and subsequently reduced chronic renal failure." (PMID 33178550, 2020). "Suramin is also an antagonist of IL-6, known to inhibit renal fibrosis in chronic kidney disease in rats." (PMID 31879244, 2020). "Previous investigations demonstrated the effect of IL-6, IL-4, and ICAM polymorphisms in end-stage renal disease patients." (PMID 31924810, 2020). "In a study of patients with end-stage renal disease, it was suggested that malnutrition was best predicted by hsCRP and IL-6 levels." (PMID 32297262, 2020). "The Chronic Renal Insufficiency Cohort Study (CRIC) study found that elevated plasma levels of high-sensitivity C-reactive protein (hs-CRP) and IL-6 were associated with LVH and systolic dysfunction in CKD patients." (PMID 32150864, 2020). "The serum levels of interleukin (IL) 1β (17.5 kDa), IL-6 (21.0–28.0 kDa), and IL-18 (18.0 kDa) as well as κ (22.5 kDa) and λ (45.0 kDa) free light chains (FLCs) are also elevated in patients with advanced chronic kidney disease (CKD)." (PMID 31892319, 2019). "VDR can form a complex with the p65 subunit of NFκB to produce anti-inflammatory actions and vitamin D supplementation has already been reported to help reducing circulating levels of IL-6 in other populations such as end-stage renal disease patients." (PMID 31179282, 2019). "SDMA in chronic kidney disease (CKD) patients was more significantly correlated to interleukin (IL)-6 and tumor necrosis factor-alpha (TNF-α) levels compared to ADMA." (PMID 31357472, 2019). "Chronic kidney disease (CKD) is associated with increased procoagulants, including cystatin C, C-reactive protein, interleukin-6, tumor necrosis factor-α soluble receptor 1, intercellular adhesion molecule-1, fibrinogen, and factor VIII." (PMID 30115029, 2018). "Chronic kidney disease results in a state of chronic low-grade inflammation, with increases seen in pro-inflammatory markers such as interleukin 6 (IL-6) and C-reactive protein (CRP), which contributes to worsened mortality outcomes in this population." (PMID 28287463, 2017). "Myostatin contributes to inflammatory conditions such as chronic kidney disease, and therapeutic blockage reduces immunopathology through the suppression of IL-6, IFN-γ and TNF-α." (PMID 26291724, 2015). "Therapies with ACE inhibitors in patients with congestive heart failure or advanced chronic renal disease have demonstrated that is associated with a significant decrease in TNF-α and IL-6 activity." (PMID 25785280, 2015). "We studied the association of inflammatory biomarkers including C-reactive protein (CRP), tumor necrosis factor-alpha (TNF-α), and interleukin-6 (IL-6) with chronic kidney disease (CKD)." (PMID 26025192, 2015).
chronic kidney disease (continued). "Both IL-1β and IL-6 are important cytokines which are essential mediators of immune response and inflammatory reactions in patients with chronic renal failure." (PMID 23990847, 2013). "In patients with end-stage renal disease, higher levels of proinflammatory cytokines such as tumor necrosis factor alpha (TNFα) and interleukin-6 (IL-6) have been consistently observed and are thought to contribute to ACD." (PMID 23053592, 2012). "Elevated plasma SDMA levels were found to correlate with inflammatory markers, such as TNF-alpha, high sensitivity CRP and Interleukin-6 (IL-6) in chronic kidney disease (CKD) patients." (PMID 23443106, 2012). "It is believed that IL-6 is the most powerful inflammatory biomarker for chronic kidney disease." (PMID 40027896, 2025). "The levels of IL-6 in the blood rise as chronic kidney disease progresses." (PMID 40027896, 2025). "Immunosuppression from conditions like malignancy, HIV, or chronic kidney disease may blunt IL-6 responses, creating survival bias if immunocompromised patients died before developing high IL-6 levels." (PMID 41439926, 2025). "In chronic kidney disease, mitochondrial dysfunction, oxidative stress, immune dysfunction, and chronic low-grade inflammation are common, as reflected by elevated levels of circulating inflammatory markers, such as IL-1β, IL-6, and C-reactive protein." (PMID 40725180, 2025). "A meta-analysis on the impact of probiotics on chronic kidney disease indicated that probiotics might also reduce the level of p-CS and increase the level of interleukin-6 (IL-6), thereby improving gastrointestinal symptoms." (PMID 40697558, 2025). "Moreover, cytokines like IL-6 or TNF can drive an inflammatory process by inducing COX-2 expression in chronic kidney disease." (PMID 40217316, 2025). "Chronic kidney disease incidence correlates with elevated systemic IL-6 levels." (PMID 41369384, 2025). "Studies have found that cytokines involved in chronic inflammation, termed “inflammaging”, or senescent-associated secretory proteins such as IL-6 and GDF-15, have been implicated with decreased survival in normal aging, disease states like end stage renal disease, and in KTx recipients." (PMID 40612959, 2025). "However, other studies showed that SARS-CoV-2 seroconversion in people with chronic kidney disease is promoted by pro-inflammatory cytokines IL-6 and IFN-γ." (PMID 38612524, 2024). "Following on from these results, an ongoing trial, ZEUS, will compare ziltivekimab with placebo in patients with chronic kidney disease and elevated hsCRP to determine if the anti-inflammatory approach of directly reducing circulating IL-6 reduces CV event rates." (PMID 37762627, 2023). "Furthermore, IL-6 in patients with T2DM is a robust trigger for the progression of chronic kidney disease, and high serum and urine IL-6 values have been proposed to be a prognostic marker for development of diabetic nephropathy." (PMID 37996879, 2023). "IL-6 is known to be increased systemically in many forms of chronic kidney disease." (PMID 36834691, 2023). "Moreover, it has also been shown that IL-6 reduces endothelial nitric oxide production and adiponectin expression, thus suggesting the role of IL-6 also in patients with chronic kidney disease by inducing chronic vascular disease." (PMID 36986882, 2023). "Starting from this trial, a still recruiting large-scale study called ZEUS will compare ziltivekimab with placebo in subjects with chronic kidney disease and elevated hsCRP to study if the reduction of IL-6 decreases the cardiovascular event rates (ClinicalTrials.gov Identifier: NCT05021835)." (PMID 37600028, 2023). "Also, IL6 expression in renal issues was extremely intensified in UUO-triggered chronic kidney disease." (PMID 36866869, 2023).